CXCR2 (C-X-C motif chemokine receptor 2)
Diseases named in the same sentence as CXCR2 in open-access papers (continued):
Sharing a sentence is not in itself a finding about the gene and the disease.
colorectal cancer (continued). "For instance, the CXCR2 antagonist, SCH-527123, was able to decrease phosphorylation of NF-κB in colorectal cancer cells while in ovarian cancer cells, CXCR2 stimulated angiogenesis by a process thought to also involve NF-κB." (PMID 24376747, 2013). "Prior studies indicate that the CXCR2 antagonist, SCH-527123, decreased Erk and Akt activation in colorectal cancer cells and that CXCR2 knockdown reduced Erk activation in ovarian cancer cells." (PMID 24376747, 2013). "Researchers have also observed a correlation between colorectal cancer (CRC)-associated gut microbiota and the expression of the CXCR2 signaling gene, suggesting a potential mechanistic link between CXCR2 signaling gene expression and alterations in specific gut microbiota." (PMID 38835386, 2024). "Dual blockade of CCR1 and CXCR2 pathways in myeloid cells could be an effective therapy against colorectal cancer." (PMID 38750114, 2024). "In addition, CXCL5 is positively correlated with the micro-vessel marker CD31, and it activates the AKT/NF-kB/FOXD1/VEGF-A pathway to enhance its tube formation ability in a CXCR2-dependent manner in colorectal cancer." (PMID 36980564, 2023). "Thus, Arnt−/− neutrophils enhanced the recruitment and function of neutrophils in a CXCR2-dependent manner coupled with gut microbiota in developing colorectal cancer in mice." (PMID 36859266, 2023). "This knowledge may offer CXCR2 as a new target to treat and prevent development of colorectal carcinoma metastases." (PMID 36260158, 2023). "In a liver metastasis model of CRC, it was observed that cancer cells upregulate the secretion of CXCL1 in TAMs in a VEGF dependent manner, which thereby attracts CXCR2-positive MDSCs to form a pre-metastatic niche in the liver to promote the metastasis of colorectal cancer cells." (PMID 34689842, 2021). "Preclinical studies have reported that CXCR2 inhibitors or anti-CXCR2 antibodies alleviate MDSCs-induced immunosuppression, thus improving the effects of anti-PD-1 therapy in rhabdomyosarcoma, pancreatic ductal adenocarcinoma, and colorectal cancer." (PMID 34336860, 2021). "Similarly, CXCR2 expression was identified as a poor prognostic marker in lung cancer, pancreatic ductal adenocarcinoma, and colorectal cancer." (PMID 34944914, 2021). "In colorectal cancer, VEGF secretion by colorectal carcinoma cells stimulates tumor-associated macrophages (TAMs) to produce chemokine (C-X-C motif) ligand 1 (CXCL1), which recruits C-X-C motif chemokine receptor 2 (CXCR2)+ MDSCs to the liver tissue." (PMID 30792719, 2019). "Additionally, CXCL5 has been demonstrated to possess the ability to activate the PI3K-AKT signalling pathway in hepatocellular carcinomas and colorectal cancer cells via its receptor CXCR2." (PMID 29665837, 2018). "Additionally, the CXCL5/CXCR2 axis has also been found to enhance human colorectal cancer metastasis through the activation of the ERK/Elk-1/Snail and AKT/GSK3β/β-catenin pathways." (PMID 29665837, 2018). "Herein, we identified the prognostic significance of CXCR2 in colorectal cancer patients." (PMID 28415702, 2017). "Additionally, although we centered our investigation on the CXCL5/CXCR2 axis as a primary signaling pathway, it's crucial to recognize that other signaling cascades may also contribute to colorectal cancer progression." (PMID 38817853, 2024). "Inhibition of CXCR1 and/or CXCR2 by pharmacological or genetic approaches showed that limiting neutrophil infiltration resulted in reduced tumor growth in murine models of pancreatic ductal adenocarcinoma, colorectal cancer, lung adenocarcinoma, and rhabdomyosarcoma." (PMID 35158948, 2022). "Since CXCR2 is the receptor for CXCL7 and is significantly expressed on colorectal cancer tumor cells, we aimed to verify the role of CXCL7 in mediating chemoresistance via CXCR2." (PMID 40368902, 2025). "By targeting the BHLHE41–CXCL1/CXCR2 signaling axis, METTL3 promotes colorectal cancer progression through remodeling of the inflammatory TME." (PMID 40986143, 2025).
colorectal cancer (continued). "In the context of colorectal cancer (CRC), the secretion of C-X-C motif chemokine ligand 1 (CXCL5) secreted by CAFs binds to C-X-C chemokine receptor type 2 (CXCR2) on tumor cells, activating the PI3K/AKT signaling pathway." (PMID 38672455, 2024). "AC modulates the CXCL8/CXCR2 chemokine axis and inhibits the PI3K/Akt/mTOR pathway in colorectal cancer cells and orthotopic mouse models, thereby exerting anti-metastatic effects on HCC." (PMID 39206194, 2024). "The CXCL1/CXCR2 and CXCL8-CXCR1/CXCR2 axes are under intensive investigation as they appear to regulate the progression and invasion of colorectal cancer (CRC)." (PMID 37509572, 2023). "CXCL5 is a predictor of poor prognosis in patients with colorectal cancer, and blocking the CXCL5- CXCR2 axis is an effective treatment strategy for them." (PMID 33955820, 2021). "Mechanistically, colorectal cancer cells stimulate TAMs to produce CXCL1 by secreting VEGFA, and CXCL1 recruits CXCR2+ MDSCs from the blood into the pre-metastatic liver." (PMID 34527668, 2021). "Bibliographic search evidenced that MAL, BANK1, CXCR2, and KCNJ15 genes play a tumor suppressive role in different types of cancer, including colorectal cancer, B-cell lymphoma, and renal cell carcinoma." (PMID 32825087, 2020). "In SL4 and CT26 colorectal cancer, tumor-infiltrated Ly6Clo monocytes induced by anti-VEGF therapy can also recruit CXCR2-expressing neutrophils to the tumor site via the CXCL5-CXCR2 and CXCL12-CXCR4 axes." (PMID 31474975, 2019). "Reports have shown that IL-8 has biological effects by binding to two chemokine receptors, CXCR1 (IL-8RA) and CXCR2 (IL-8RB), which are members of the seven transmembrane G-protein-coupled receptor (GPCR) family in human colorectal cancer." (PMID 27557518, 2016). "In colorectal cancer, upregulated FOXD1 drives VEGF-A-dependent angiogenesis via CXCR2." (PMID 40999468, 2025). "Therefore, CXCR2 signaling is required for ARNT-directed neutrophil recruitment and function while contributing to colorectal cancer development and growth." (PMID 36859266, 2023). "They concluded that CXCL5 may serve as a promoter of colorectal cancer metastasis and a predictor of poor clinical outcomes in colorectal cancer patients and inhibition of the CXCL5/CXCR2 signaling pathway may be a promising target for CRC therapy." (PMID 37848726, 2023). "Moreover, it was shown that primary tumor cells (of colorectal carcinoma) secrete VEGF-A, stimulating TAMs to produce CXCL1, which recruits CXCR2+ MDSCs to form a pre-metastatic niche that promotes liver metastasis." (PMID 36260158, 2023). "In a mouse model of colorectal cancer, resistance to anti-PD-1 therapy observed in KRASG12D-expressing colon tumors could be overcome by inhibition of CXCR2." (PMID 35158948, 2022). "The absence of CXCR2 prevented colon cancer cell growth and CXCL1, a CXCR2 ligand, was inversely associated with recurrence-free survival in colorectal cancer patients." (PMID 27723802, 2016). "Furthermore, CCR1+ and CXCR2+ myeloid cells were concentrated around the tumor invasion front in our mouse model, which is consistent with a previous human CRC study and data from a public database from human colorectal cancers." (PMID 38750114, 2024). "Additionally, overexpression of CXCL5 enhanced the migration and invasion of colorectal cancer cells by inducing the epithelial-mesenchymal transition (EMT) through activation of the ERK/Elk-1/Snail pathway and the AKT/GSK3β/β-catenin pathway in a CXCR2-dependent manner." (PMID 28356111, 2017). "CXCR2 is required for NET development, cytokine production and recruitment of neutrophils but not the suppressive activities induced by Arnt−/− in colorectal cancer." (PMID 36859266, 2023).
hepatocellular carcinoma (58 papers, 2015 to 2025). A malignant tumor that arises from hepatocytes. "The subgroup analyses revealed that high CXCR2 expression was associated with poor prognosis of most digestive system cancers, including hepatocellular carcinoma, gastric cancer, and esophageal cancer." (PMID 29312644, 2017). "Several studies have shown that CXCR2 overexpression was associated with poor survival in gastric cancer, hepatocellular cancer, and renal cell cancer." (PMID 29312644, 2017). "Shi M et alfound a three-gene expression signature associated to early human hepatocellular carcinoma, constituted by the chemokine (C-X-C motif) receptor 2 (CXCR2), C–C chemokine receptor type 2 (CCR2) and the E1A-Binding Protein P400 (EP400)." (PMID 26317806, 2015). "C-X-C chemokine receptor type 2 (CXCR2) antagonist AZD5069 overcame immunotherapy secondary resistance in hepatocellular carcinoma by targeting myeloid interleukin-8/CXCR2 signaling." (PMID 40539064, 2025). "Here, we analyze the percentage of CD14+CXCR2+ monocyte subsets in hepatocellular carcinoma (HCC) patients, and investigate the mechanisms that regulate CXCR2 surface expression on monocytes and its biological function." (PMID 37403022, 2023). "The down-regulation of CXCR2 expression affected the tumor-killing activity of monocytes on primary hepatoma cells." (PMID 37403022, 2023). "used Glypican‐3 (GPC3) CAR‐T cells expressing CXCR2 (CXCR2 CAR‐T) to treat hepatocellular carcinoma which showed relatively high expressions of several CXCR2 ligands." (PMID 36495108, 2022). "It should be emphasised that, although CXCL5 and CXCR2 were mentioned, similar to anti-tumour chemokines, the CXCL5/CXCR2 axis, instead, can contribute to tumour invasion in hepatocellular carcinoma." (PMID 35406451, 2022). "Accordingly, the authors co-expressed CXCR2 in glypican-3-targeting CAR T cells for enhanced hepatocellular carcinoma homing." (PMID 34885108, 2021). "In a murine model of hepatocellular carcinoma, treatment with CXCR2-modified CAR T cells significantly reduced tumor burden and enhanced intra-tumoral T-cell infiltration." (PMID 34944914, 2021). "A meta-analysis of 4012 patients with solid tumors from 21 different studies found that CXCR2 expression was predictive of poor prognosis of patients with hepatocellular carcinoma, gastric cancer, or esophageal cancer." (PMID 34944914, 2021). "The CXCR2/CXCL5 axis was also found to enhance epithelial-mesenchymal transition of hepatocellular carcinoma cells through the activation of the PI3K/AKT/GSK-3β/Snail signaling." (PMID 29743818, 2018). "Neutrophils express CXCR2, and its expression was correlated with poor prognosis of hepatocellular carcinoma patients." (PMID 28575019, 2017). "Decreased miR-940 in hepatocellular carcinoma acted as an adaptor of CXCR2 and suppressed the invasion and migration of HCC cells." (PMID 28594854, 2017). "In conclusion, our data indicated that miR-940 negatively regulates cell invasion and migration in hepatocellular carcinoma though regulation of CXCR2, which results in promotion of invasion and metastasis." (PMID 27807540, 2016). "Previous studies have confirmed that IL-8 receptors (CXCR1 and CXCR2) are expressed on the surface of hepatoma cells." (PMID 26593962, 2015). "Also, CXCR2+ MDSCs are the primary subpopulation mediating immune escape in the TME of pancreatic and hepatocellular carcinoma, which can be reversed by CXCR2 antagonists." (PMID 37795038, 2023). "CXCR2/CXCL5 axis could activate PI3K/AKT signaling in hepatocellular carcinoma cells and also activate the STAT3 signaling pathway to promote the migration and invasion in gastric cancer." (PMID 33458757, 2021). "Under the synergistic effect of radiotherapy, anti‐CPG3‐NK92 cells engineered with CXCR2 displayed potent cytotoxicity against hepatocellular carcinoma (HCC), though the antitumor effect varied with different radiation doses." (PMID 40525700, 2025).
hepatocellular carcinoma (continued). "The mutual binding of CXCL8 to CXCR2 activates downstream signaling pathways and enhances the invasiveness of various tumors, including hepatocellular carcinoma (HCC), making it a potential therapeutic target." (PMID 40006729, 2025). "Interestingly, another study also reported that chronic psychological stress could induce higher expression of CXCR2 on myeloid cells via activating β-adrenergic receptor signaling in hepatocellular carcinoma." (PMID 37210553, 2023). "Human hepatocellular carcinoma (HCC) tumor tissues and cell lines express several chemokine ligands for CXCR2, however, both human peripheral T cells and TILs of HCC lack expression of CXCR2." (PMID 35432319, 2022). "Furthermore, high CXCR2 expression has also been reported in hepatocellular carcinoma." (PMID 36118530, 2022). "Similarly, CXCR2 (C-X-C chemokine receptor type 2), which is often overexpressed in hepatocellular carcinoma (HCC) patients, has also been recognized as an indicator of poor prognosis in various cancers, including liver cancer." (PMID 41024300, 2025). "AZD5069, a CXCR2 inhibitor that is used to reduce absolute neutrophil recruitment in bronchiectasis patients, is also under a phase I/II study in combination with durvalumab in patients with advanced hepatocellular carcinoma (HCC)." (PMID 38474175, 2024). "The CXCR2-knockdown or control THP-1 cells were treated with IL-8 and then co-cultured with the primary hepatoma cell line HepG2." (PMID 37403022, 2023). "The enforced expression of CXCR2 on CAR T cells increased migration and accumulation within tumours in a hepatocellular carcinoma tumour model, improving treatment outcomes." (PMID 35205725, 2022). "CXCR2-modified CAR-T cells enhance trafficking capacity, which improves therapeutic response in hepatocellular carcinoma." (PMID 34840630, 2021). "Additionally, SRY, via its downstream target SOX9, promotes hepatocellular carcinoma (HCC) progression by upregulating CXCL5 expression and activating the CXCL5/CXCR2 signaling axis, thereby enhancing tumor cell proliferation and invasion." (PMID 40438106, 2025). "The CXCL2/CXCR2 axis also plays a role in immune evasion and resistance to therapy in different types of cancer, where SB225002 suppresses recruiting neutrophils and tumor growth under stress in hepatocellular carcinoma models." (PMID 41155662, 2025). "Additionally, CXCR2 (CXC chemokine receptor type 2), which is often highly expressed in patients with hepatocellular carcinoma, is also recognized as a poor prognostic marker across various tumor types, including liver cancer." (PMID 40006729, 2025). "Hepatocellular carcinoma tumours secrete various CXCR2-binding chemokines, but CXCR2 is not expressed on peripheral T cells or tumour infiltrating cells." (PMID 35205725, 2022). "Receptor-interacting protein kinase 3 (RIP3) knockdown promotes tumor progression and immune escape through driving MDSC recruitment by CXCR2 and decreasing interferon (IFN)-γ+ CD8+ T cells in hepatocellular carcinoma (HCC)." (PMID 35011369, 2021). "The RIP3 deletion in hepatocellular carcinoma (HCC) is revealed to increase the production of chemokine the CXCL1 by activating the NF-κB pathway, which results in chemoattracting CXCR2+MDSC into cancer site." (PMID 34689842, 2021). "In another study, CXCR2-expressing anti-glypican-3 (GPC3)-CAR-T cells showed improved migration and activity in a xenograft hepatocellular carcinoma (HCC) tumour model." (PMID 32722109, 2020). "Addition of CXCR2 expression by GPC3-targeted CAR T cells has previously been shown to increase homing and produce greater in vivo anti-tumoral effects in a mouse xenograft model of hepatocellular carcinoma (HCC)." (PMID 38554158, 2024).
ovarian carcinoma (52 papers, 2004 to 2026). A malignant neoplasm originating from the surface ovarian epithelium. "A study of CXCR1 and CXCR2 activation by IL-8 and inhibition by reparixin confirmed that CXCR2 was primarily present on ovarian cancer cells, and its high expression was strongly associated with shorter survival and increased metastatic potential." (PMID 34572929, 2021). "Increasing evidence has implicated a high expression of CXCR2 in advanced stage of ovarian carcinomas leading to increased cancer progression and enhanced angiogenesis." (PMID 29515768, 2018). "CXCR2 has been implicated in cell cycle and apoptosis via several molecular pathways in ovarian cancer." (PMID 29515768, 2018). "We analyzed the somatic mutation of CXCR2 in ovarian cancer." (PMID 34840630, 2021). "Amplification was the main mutational type of CXCR2 in ovarian cancer." (PMID 34840630, 2021). "Amplification was the major mutational type of CXCR2 in ovarian cancer." (PMID 34840630, 2021). "Furthermore, the level of IL‐8 and its receptors CXCR1 and CXCR2 expression were associated with ovarian cancer stage, grade and lymph node metastasis." (PMID 31793192, 2020). "Nonetheless, it has been demonstrated that ectopic expression of CXCR2 in T-cells from normal donors or tumor-associated lymphocytes from ovarian cancer patients can increase their migration towards recombinant IL-8 and autologous ascites that contains CXCL1 and CXCL8 (IL-8)." (PMID 31091832, 2019). "Interestingly, increased expression of CXCR2 in ovarian cancer cells was associated with diminished apoptosis." (PMID 28303009, 2017). "These ligands, similar to CXCR2, are important in the formation of intraperitoneal cavity metastasis in ovarian cancer." (PMID 37108425, 2023). "The overexpression of CXCR2 in tumor cells can lead to ovarian cancer progression by enhancing NF-κB activation via EGFR-transactivated Akt signaling, thereby upregulating the expression of pro-inflammatory chemokines." (PMID 37765018, 2023). "To characterize the expression profiles of CXCR1 and CXCR2 in the tumor microenvironment of ovarian cancer tumors, we checked IHC staining in the HPA." (PMID 37765018, 2023). "The results of this study indicate that CXCR3/4/7 are potential targets for the treatment of ovarian cancer, and CXCR2/4/5/6/7 are new markers for the prognosis of ovarian cancer." (PMID 33829065, 2021). "Despite this, the functions of CXCR2 in prognosis and immunology in ovarian cancer remain ambiguous." (PMID 34840630, 2021). "For observing the function of CXCR2 expression on tumor progression, this study separated ovarian cancer specimens into high- and low-expression groups in line with CXCR2 expression." (PMID 34840630, 2021). "Based on three algorithms, CXCR2 expression negatively modulated macrophage infiltration in ovarian cancer." (PMID 34840630, 2021). "The ONCOMINE online database was used to compare the expression of CXCR1/CXCR2 mRNA in normal ovarian and ovarian cancer tissues." (PMID 33829065, 2021). "Collectively, CXCR2 acts as a promising prognostic and immunological biomarker as well as a novel immunotherapeutic target of ovarian cancer." (PMID 34840630, 2021). "CXCR2-relevant genes were identified, and their biological functions were investigated in ovarian cancer." (PMID 34840630, 2021). "Through three algorithms (TIMER, quanTIseq, and xCell), we assessed the relationships of CXCR2 with immune cell infiltration in ovarian cancer." (PMID 34840630, 2021). "CXCR2-relevant genes were markedly enriched in immunity activation and carcinogenic pathways in ovarian cancer." (PMID 34840630, 2021). "In this study, we aimed to evaluate the prognostic and immunological significance of CXCR2 in ovarian cancer." (PMID 34840630, 2021). "Especially, CXCR2 expression presented marked upregulation in ovarian cancer as well as its upregulation contributed to more undesirable survival outcomes." (PMID 34840630, 2021).